VAPB (VAMP associated protein B and C)
Diseases named in the same sentence as VAPB in open-access papers (continued):
Sharing a sentence is not in itself a finding about the gene and the disease.
Parkinson disease (18 papers, 2015 to 2025). A progressive degenerative disorder of the central nervous system characterized by loss of dopamine producing neurons in the substantia nigra and the presence of Lewy bodies in the substantia nigra and locus coeruleus. "α-Syn interacts with VAPB, and its overexpression or Parkinson’s-associated mutations disrupts the VAPB–PTPIP51 interaction, thereby diminishing the contact sites between ER and mitochondria." (PMID 41367495, 2025). "There is a precedent for this since Parkinson's disease‐linked α‐synuclein binds to VAPB to disrupt its interaction with PTPIP51." (PMID 35026048, 2022). "Disruption of the VAPB‐PTPIP51 tethers by Parkinson's disease‐linked α‐synuclein involves its direct binding to VAPB, and GSK3β is a known negative regulator of the VAPB‐PTPIP51 interaction." (PMID 35026048, 2022). "Overexpression wild-type and familial Parkinson’s disease mutant α-synuclein disrupt the interaction between VAPB and PTPIP51 to loosen ER–mitochondria associations." (PMID 36611869, 2022). "Notably, disruption to the VAPB-PTPIP51 tethers has been linked to Parkinson’s disease and FTD/ALS." (PMID 30841933, 2019). "The Parkinson’s disease (PD)-related protein, α-synuclein, binds to VAPB and disrupts the interaction between VAPB and PTPIP51, which leads to the loss of contact between ER and mitochondria." (PMID 32626703, 2020). "Damage to ER-mitochondria contacts and signaling is increasingly linked to these diseases and for Parkinson’s disease and FTD/ALS this includes disruption to the VAPB-PTPIP51 ER-mitochondria tethering proteins." (PMID 30841933, 2019). "Here we show that α-synuclein binds to VAPB and that overexpression of wild-type and familial Parkinson’s disease mutant α-synuclein disrupt the VAPB-PTPIP51 tethers to loosen ER–mitochondria associations." (PMID 28337542, 2017). "Moreover, damage to the VAPB-PTPIP51 tethers and ER-mitochondria signaling is linked to the major human neurodegenerative diseases: Alzheimer’s disease, Parkinson’s disease and FTD/ALS." (PMID 36120587, 2022). "Such knowledge is essential for determining whether disruption to ER-mitochondria signaling and the VAPB-PTPIP51 tethers contributes to synaptic dysfunction in Parkinson’s disease and FTD/ALS." (PMID 30841933, 2019). "Such knowledge is essential not only for comprehending the normal roles of ER-mitochondria signaling in synaptic function, but also for determining any pathological role that disruption to the VAPB-PTPIP51 tethers might play in Parkinson’s disease and FTD/ALS." (PMID 30841933, 2019). "Thus, damage to the VAPB-PTPIP51 tethers may contribute to synaptic dysfunction in Parkinson’s disease and FTD/ALS." (PMID 30841933, 2019). "Thus, expression of both wild-type and mutant α-synuclein reduces ER–mitochondria associations and the VAPB–PTPIP51 interaction in a number of different assays and this includes in dopaminergic neurons derived from familial Parkinson’s disease patients carrying SNCA gene triplication." (PMID 28337542, 2017). "In addition, mutations in the endo-lysosomal trafficking machinery have been implicated in neurodegenerative disorders including ALS and FTD (CHMP2B, FIG4, VAPB, and VCP) and defects in retrograde trafficking increase the risk for Parkinson's disease (VPS35)." (PMID 26357016, 2015). "One such connection is formed by the interaction of the surface proteins such as VAPB-PTPIP51 and is reported to be disrupted in degenerating neuronal conditions, like ALS, Parkinson, and FTD." (PMID 36968195, 2023). "This is because of their roles in several key cellular functions and because disruption to the VAPB-PTPIP51 interaction is seen in Alzheimer’s disease, Parkinson’s disease, and FTD/ALS." (PMID 36120587, 2022). "PLAs including ones for VAPB and PTPIP51 have already been used to quantify ER-mitochondria contacts and signaling in models of ALS, Parkinson’s disease and Alzheimer’s disease." (PMID 36051435, 2022).
Parkinson disease (continued). "For Parkinson’s disease and FTD/ALS, this damage has been shown to involve disruption to the ER-mitochondria tethering proteins VAPB and PTPIP51 which function to recruit regions of ER to the mitochondrial surface." (PMID 30841933, 2019). "Our results reveal a new role for the VAPB-PTPIP51 tethers in neurons and suggest that damage to ER-mitochondria signaling contributes to synaptic dysfunction in Parkinson’s disease and FTD/ALS." (PMID 30841933, 2019). "As detailed above, damage to ER-mitochondria signaling has been associated with Alzheimer’s disease, Parkinson’s disease and FTD/ALS and for Parkinson’s disease and FTD/ALS this can involves disruption of the VAPB-PTPIP51 tethers." (PMID 30841933, 2019). "Moreover, damage to the VAPB-PTPIP51 tethers has been described in Alzheimer’s disease, Parkinson’s disease and FTD/ALS." (PMID 40045432, 2025). "The VAPB-PTPIP51 interaction is disrupted in Alzheimer’s disease, Parkinson’s disease, FTD and ALS." (PMID 40045432, 2025). "We also provide evidence that UDCA, an FDA approved drug that along with analogues is in clinical trials for ALS, Parkinson’s disease and Alzheimer’s disease but whose precise therapeutic target is unclear, rescues TDP43 induced damage to the VAPB-PTPIP51 interaction." (PMID 38395965, 2024). "Moreover, there is evidence that the VAPB-PTPIP51 interaction is also disrupted in Alzheimer’s disease and Parkinson’s disease; notably TDP43 pathology is a feature of both these diseases." (PMID 38395965, 2024). "Immunofluorescence analysis (IFA) showed a peculiar pattern of VAPB aggregates in sALS, not evident in healthy control (HC) subjects and in Parkinson’s disease (PD) PBMCs." (PMID 31936602, 2020). "Loss of neuronal synaptic function is a key feature of Parkinson’s disease and FTD/ALS but the roles that ER-mitochondria signaling and the VAPB-PTPIP51 tethers play in synaptic function are not known." (PMID 30841933, 2019). "Suspecting atypical Parkinsonism, a Wilson disease study and genetic tests of Charcot–Marie–Tooth (CMT), atypical Parkinsonisms (PARKs, GAB, DNAJC6, VPS13C, PINK, and LG), and atypical spinal–muscular atrophies (DYNC1H1, BICD, VAPB, GARS, DYNC1H1, mtATP6, and mtATP8) were carried out." (PMID 37510225, 2023).
frontotemporal dementia (15 papers, 2014 to 2025). Frontotemporal dementia (FTD) comprises a group of neurodegenerative disorders, characterized by progressive changes in behavior, executive dysfunction and language impairment, as a result of degeneration of the medial prefrontal and frontoinsular cortices. "Moreover, we demonstrate that TDP-43, a protein pathologically linked toamyotrophic lateral sclerosis and fronto-temporal dementia perturbsER–mitochondria interactions and that this is associated with disruptionto the VAPB–PTPIP51 interaction and cellular Ca2+homeostasis." (PMID 24893131, 2014). "Similarly, mutations in VAPB play a role in ALS and affect intracellular transport and ER stress but also contribute to neurodegeneration in PD and frontotemporal dementia." (PMID 40724909, 2025).
motor neuron disease (14 papers, 2011 to 2025). "While strong effects of VAP deletion in cultured cells are obtained only when both homologues are silenced, the studies with mice specifically deleted for VAPB are in partial agreement with a pathogenic role of VAPB haploinsufficiency in motor neuron disease." (PMID 25409455, 2014). "Recently, ALS8 was identified from a large Brazilian family with dominant motor neuron diseases, which encodes a mutated VAPB (vesicle-associated membrane protein-associated protein B)." (PMID 22069488, 2011). "Among the catalogued ALS-like motor neuron diseases, mutations in SOD1 (ALS1), FUS/TLS (ALS6), VAPB (ALS8), ANG (ALS9), TARDBP (ALS10), FIG4 (ALS11) and a hexanucleotide-repeat expansion (GGGGCC) in the C9ORF72 cause adult onset neurodegenerative disorder." (PMID 22384259, 2012). "Indeed, gene mutations of VAPB have been found in several families developing ALS8, a motor neuron disease also affecting the autonomic nervous system." (PMID 29879376, 2018). "A major question arising from our results is whether this novel function of VAPB in regulating HCN1 and HCN2 activities could be involved in motor neuron disease." (PMID 29879376, 2018). "The VAPB network and further mechanistic understanding of interactions with key pathways, such as the TOR cassette, will pave the way for a better understanding of the mechanisms of onset and progression of motor neuron disease." (PMID 25361581, 2014).
spinal muscular atrophy (10 papers, 2013 to 2025). A motor neuron disease that affect the muscles, and characterized by muscle weakness and atrophy resulting from progressive degeneration and irreversible loss of the anterior horn cells in the spinal cord (i.e., lower motor neurons) and the brain stem nuclei. "The VAPB mutation was reported to be associated with Spinal Muscular Atrophy (ClinVar Submission Accession SCV000434613)." (PMID 34686194, 2021). "The P56S mutation in vesicle-associated membrane protein-associated protein B (VAPB) leads to fALS (ALS8) and spinal muscular atrophy (SMA)." (PMID 33972508, 2021). "In 2004, Mayana Zatz's group discovered a novel causative genetic locus, VAMP-associated protein B (VAPB), termed as ALS8, in a large Brazilian family whose members succumbed to ALS and/or spinal muscular atrophy." (PMID 30635270, 2019).
Alzheimer disease (8 papers, 2018 to 2025). A progressive, neurodegenerative disease characterized by loss of function and death of nerve cells in several areas of the brain leading to loss of cognitive function such as memory and language. "In these post-mortem Alzheimer’s disease cases, disruption to the VAPB-PTPIP51 interaction occurs early in disease arguing that it contributes to the pathogenic process in a primary fashion and is not just some epiphenomena." (PMID 38395965, 2024). "Most recently, such studies have been extended to analyses of the VAPB-PTPIP51 interaction in human post-mortem Alzheimer’s disease brains." (PMID 36051435, 2022). "It would also be interesting to investigate the VAPB-PTPIP51 tethers in Alzheimer’s disease models." (PMID 40045432, 2025). "However, the VAPB/PTPIP51 reductions in Alzheimer’s disease are restricted to late-stage disease whereas breaking of the tethers is an early disease feature." (PMID 40045432, 2025). "Interestingly, Alzheimer’s disease and FTD linked Tau which forms the neurofibrillary tangle pathology in these diseases may also activate GSK3β to disrupt the VAPB-PTPIP51 interaction and ER-mitochondria signaling functions." (PMID 40045432, 2025). "This includes VAPB-PTPIP51 disruption in induced pluripotent stem cell derived dopaminergic neurons from familial Parkinson’s disease patients carrying pathogenic SNCA (α-synuclein) triplications and in affected neurons in post-mortem Alzheimer’s disease brain." (PMID 38395965, 2024). "Despite the evidence from human post-mortem studies showing an early disruption of VAPB-PTPIP51 binding, a number of other studies report an up-regulation of ER-mitochondria signaling functions in Alzheimer’s disease." (PMID 40045432, 2025). "There is evidence that VAPB and PTPIP51 protein levels are reduced in disease; lower levels of both VAPB and PTPIP51 are seen in an affected region of post-mortem Alzheimer’s disease brains (temporal cortex) and lower levels of VAPB are seen in ALS spinal cord." (PMID 40045432, 2025). "In addition, for Alzheimer's disease and other neurodegenerative diseases, the molecular mechanism of MAMs has not been fully understood, but we can analyze the existing literature to show that key proteins such as Sig‐1R, IP3R, and VAPB play an important role in most neurodegenerative diseases." (PMID 40406921, 2025).
breast carcinoma (7 papers, 2012 to 2023). "Although aberrant expression of VAPB is associated with breast cancer, its function in tumor cells is poorly understood." (PMID 23049696, 2012). "Because the VAPB allele is often amplified in human breast cancer, including cancers that have HER2-amplification,we sought to determine if elevated VAPB expression enhances tumor cell growth." (PMID 23049696, 2012). "A genome-wide microarray analysis of 50 human breast cancer cell lines and 145 clinical specimens revealed that VAPB is often amplified and/or overexpressed in breast cancer." (PMID 37945695, 2023). "The remarkable versatility of VAPB across diverse cellular contexts, demonstrated by its role in driving the proliferation of breast cancer cells, lends additional weight to its examination within the framework of medulloblastoma." (PMID 37945695, 2023). "Genome-wide microarray analyses of 50 breast cancer cell lines and 145 primary breast tumors revealed that the VAPB gene is often amplified and, thereby, that its transcript is overexpressed in breast cancer." (PMID 33503978, 2021). "A genome-wide microarray analysis demonstrated that VAPB has been frequently overexpressed or amplified in breast cancer." (PMID 23874428, 2013). "Collectively, the genetic, functional and mechanistic analyses suggest a role of VAPB in tumor promotion in human breast cancer." (PMID 23049696, 2012). "In summary, we identified a functional role of VAPB in promoting tumor cell proliferation in breast cancer." (PMID 23049696, 2012). "To determine the impact of VAPB expression on clinical outcome in human breast cancer, we analyzed VAPB expression in a published human breast cancer microarray dataset from a panel of 295 patient samples." (PMID 23049696, 2012). "Taken together these data highlight the clinical relevance of high VAPB expression in human breast cancer." (PMID 23049696, 2012). "A genome-wide microarray analysis of 50 human breast cancer cell lines and 145 clinical specimens revealed that VAPB is often amplified or overexpressed in breast cancer." (PMID 23049696, 2012). "We analyzed the expression of VAPB in both a breast cancer tissue microarray and two published large mRNA expression datasets and correlated VAPB expression with clinical outcomes." (PMID 23049696, 2012). "While parental or vector control tumors display densely packed tumor cells, VAPB knockdown tumors exhibit a reduced mammary tumor cell content." (PMID 23049696, 2012). "The growth regulation of mammary tumor cells controlled by VAPB appears to be mediated, at least in part, by modulation of AKT activities." (PMID 23049696, 2012). "In this report, we provide evidence that VAPB regulates mammary tumor growth and proliferation via activation of AKT activity." (PMID 23049696, 2012). "Next, we investigated the role of VAPB in tumor growth in vivo in a mammary tumor orthotopic transplantation model." (PMID 23049696, 2012). "The growth regulation of mammary tumor cells controlled by VAPB appears to be mediated, at least in part, by modulation of AKT activity." (PMID 23049696, 2012). "Several studies reported an increase in VAPB copy number or expression in breast cancer." (PMID 23049696, 2012). "In this report, we studied the role of VAPB in breast cancer." (PMID 23049696, 2012). "Interestingly, Arf1 has also been implicated in recruitment of p85 subunits of PI3K to EGFR in breast cancer cells, providing an additional possible mechanism by which VAPB could regulate AKT activities." (PMID 23049696, 2012). "Other notable genes decreased by SK1 KD were NDUFA2 in prostate and E2F5, NAGK, VAPB, NFATC3, CDK2 in breast cancer cell lines." (PMID 30971929, 2019). "To assess VAPB protein expression in human breast cancer, we performed immunohistochemistry in breast cancer tissue microarrays (TMA, n=84) with a previously validated anti-VAPB antibody." (PMID 23049696, 2012).
breast carcinoma (continued). "Conversely, knockdown of VAPB in MMTV-Neu mammary tumor cells inhibited tumor cell proliferation in 3-D culture in vitro and suppressed tumor growth in orthotopic mammary tumor allografts." (PMID 23049696, 2012). "Meanwhile, several other risk model genes were identified in this study (ST6GALNAC4, PLPP2, ELOVL1, HACD1, VAPB, CERS2, ALDH3B2, and HACD3) have not yet been explored in depth in breast cancer." (PMID 36059802, 2022).
motor neuron degeneration (5 papers, 2013 to 2021). "Both the mutations in the VAPB domain lead to VAPB aggregation into immobile ER clusters which causes lower level of VAPB, resulting in a decreased ER anchoring of lipid-binding proteins and motor neuron degeneration." (PMID 23941283, 2013). "YIF1A and possibly YIF1B interact with VAPB and its mutant VAPB-P56S, which has been linked to motor neuron degeneration in amyotrophic lateral scleroses type 8, indicating the interactions of the YIPF proteins with VAPB may have a significant role in the pathology of the mutant VAPB." (PMID 34350187, 2021). "Consistent with previous studies our data show that neuron-specific mutant VAPB transgenic mice generally do not develop motor symptoms and signs of motor neuron degeneration." (PMID 24252306, 2013).
dementia (4 papers, 2019 to 2026). Loss of intellectual abilities interfering with an individual's social and occupational functions. "In postmortem HIV-infected frontal cortex, VAPB was paradoxically elevated yet correlated with worsening dementia severity, consistent with transcriptional upregulation that cannot overcome posttranslational blockade of VAPB-MAM localization." (PMID 42092489, 2026). "A recent study reports a reduction of VAPB and PTPIP51 interaction in the pyramidal cortex of patients with early/mid dementia, and a reduction of the expression of both VAPB and PTPIP51 in the cortex of AD patients at late-stages." (PMID 33327665, 2020).
breast tumors (3 papers, 2012 to 2021). "VAPB protein expression is elevated in primary and metastatic tumor specimens, and VAPB mRNA expression levels correlated negatively with patient survival in two large breast tumor datasets." (PMID 23049696, 2012). "Our results suggest that VAPB enhances breast tumor cell proliferation is mediated through the AKT pathway." (PMID 23049696, 2012). "In this report, we provide evidence that VAPB regulates breast tumor cell proliferation and AKT activation." (PMID 23049696, 2012).
epilepsy (3 papers, 2018 to 2025). A brain disorder characterized by episodes of abnormally increased neuronal discharge resulting in transient episodes of sensory or motor neurological dysfunction, or psychic dysfunction. "Modulating ER–mitochondria tethering via the VAPB‐PTPIP51 complex presents a potential new therapeutic strategy for epilepsy." (PMID 41456957, 2025). "Overall, the VAPB‐PTPIP51 complex represents a promising target for therapeutic intervention in epilepsy, offering potential benefits by modulating Ca2+ signaling and autophagy." (PMID 41456957, 2025). "MAMs‐related proteins (e.g., VAPB and VDAC1) may serve as early diagnostic biomarkers for epilepsy." (PMID 41456957, 2025). "VAPB modulation of HCN channels might be highly relevant for our understanding of many diseases such as cardiac arrhythmias, epilepsies, inflammatory or neuropathic pain, and ALS." (PMID 29879376, 2018). "Modulating VAPB‐PTPIP51 tethering may enhance autophagic processes, thereby reducing the pathological accumulation of proteins and damaged organelles that contribute to epilepsy pathogenesis." (PMID 41456957, 2025).
familial amyotrophic lateral sclerosis (3 papers, 2021 to 2025). An instance of amyotrophic lateral sclerosis that is caused by an inherited modification of the individual's genome. "On the other hand, mutations in the VAPB gene have been implicated in familial amyotrophic lateral sclerosis, and it has been reported that mutant VAPB proteins aggregate abnormally in neuronal cells." (PMID 36982858, 2023). "In 2004, it was discovered that a mutation (p.P56S) in the VAPB paralogue causes a rare form of dominantly inherited familial amyotrophic lateral sclerosis (ALS8)." (PMID 34440634, 2021).